PAX8 (paired box 8)
Diseases named in the same sentence as PAX8 in open-access papers (continued):
Sharing a sentence is not in itself a finding about the gene and the disease.
renal carcinoma (18 papers, 2013 to 2025). A carcinoma arising from the epithelium of the renal parenchyma or the renal pelvis. "PAX-8 is a "master regulator" of gene expression during kidney development and has been found to be increased in renal carcinomas as in our patient." (PMID 39564030, 2024). "Several previous studies have reported that PAX8 is expressed at high levels in specific types of tumor, including thyroid and renal carcinomas and pancreatic neuroendocrine tumors." (PMID 23425942, 2013). "In addition to renal cancer, E8:128132 and E8:128526 showed DNA accessibility in normal cells derived from the kidney, and PAX8 depletion inhibited the proliferation of HK2 cells, a renal epithelial cell line, and normal human renal organoids." (PMID 35676472, 2022). "In these cases the differential diagnosis requires the use of other markers such as S-100 and other tumour specific proteins according to the presumed origin (e.g PSA for prostatic carcinoma, glypican 3 for hepatocellular carcinoma, PAX8 for renal carcinoma and CDX-2 for colorectal carcinoma)." (PMID 26888362, 2016). "PAX8 is not only crucial for determining cell fate during the development of the thyroid, kidney and Müllerian system, but has also been found to be expressed at high levels in thyroid and renal carcinomas and pancreatic neuroendocrine tumors." (PMID 23425942, 2013). "Moreover, these tumor cells express renal cancer markers such as PAX8, PAX2, and CD10." (PMID 40738062, 2025). "The combined high expression of PAX8 and HNF1B was evident in renal cancers and normal tissues of the renal epithelial lineage at different developmental stages." (PMID 35676472, 2022). "Some studies have indicated the expression of the PAX8 and PAX2 markers in various renal carcinomas in adults, and these markers were known as useful markers in identifying kidney origin tumors." (PMID 34306127, 2021). "Among these genes, PAX8 and HNF1B play a key role in renal carcinoma." (PMID 30942869, 2019). "We are currently unable to classify the ovarian/renal cancer profile into ovarian and renal cancers by positive PAX-8 expression, because specific markers are not available for renal cancer profiling." (PMID 29433539, 2018). "However, even though some reports have described the expression of neuroendocrine markers in renal cancer, the tumors formed by PAX8 inhibition-resistant cells did not specifically express molecular neuroendocrine markers." (PMID 37554444, 2023).
anaplastic thyroid carcinoma (17 papers, 2005 to 2025). "Conversely, anaplastic thyroid carcinomas retain cytokeratin expression in approximately 70% of cases with 54 − 70% of them also exhibiting strong PAX8 staining, whereas reactivity for vascular markers is only focal and observed in a minor subset of tumors." (PMID 39422760, 2024). "In follicular, papillary, and anaplastic thyroid carcinomas, targeting the PAX8/peroxisome proliferator-activated receptors (PPARs) fusion protein is being considered as a potential mechanism for therapy." (PMID 34540435, 2021). "Histone methylation modifiers, such as enhancer of zeste homolog 2 (EZH2), have been shown to be overexpressed in anaplastic thyroid carcinoma cells, suppressing PAX-8 transcription." (PMID 33543394, 2021). "Although PAX8 was immunoreactive and thus worrisome for anaplastic thyroid carcinoma, the tumor was eventually proven to represent PAX5 positive diffuse large B-cell lymphoma expressing cross-reactivity with polyclonal PAX8 antibody." (PMID 28078156, 2016). "In this study, the anaplastic thyroid carcinoma ARO cells were stably transfected with a Pax8 gene expression vector." (PMID 16029487, 2005). "In this study we analysed the effects of Pax8 overexpression on a human thyroid anaplastic cancer cell line ARO cells." (PMID 16029487, 2005). "In addition, anaplastic thyroid carcinomas can also display areas with squamous change and express PAX8 as also detected in primary squamous cell carcinoma of the thyroid." (PMID 32632840, 2020). "PAX-8 immunostaining is therefore valuable in the diagnosis of anaplastic thyroid cancers." (PMID 32748087, 2020). "PAX-8 has been found to be positive in up 79% of anaplastic thyroid carcinomas." (PMID 27774331, 2016). "It induces the expression of differentiation markers (TTF1, TTF2, Pax8, and sodium/iodide symporter (NIS)) in anaplastic thyroid carcinoma through the activation of Notch1 signaling, thereby suppressing cell growth." (PMID 40943396, 2025). "Resveratrol, for example, has been shown to induce redifferentiation markers (TTF1, TTF2, Pax8, NIS) in anaplastic thyroid carcinoma cells through the activation of Notch1 signaling." (PMID 40943396, 2025). "PAX8 staining (seen in 36–76% cases), TTF1 and focal keratin positivity also helps in confirming an anaplastic carcinoma of thyroid." (PMID 38438897, 2024). "Anaplastic thyroid carcinoma was diagnostically excluded because of the colloid production, only mild nuclear pleomorphism, and diffuse TTF1 and PAX8 reactivity." (PMID 34997561, 2022). "Lack of nuclear beta-catenin expression in the stroma, lack of follicular epithelial differentiation, positivity for PAX8 and/or TTF1, and presence of increased proliferative activity are features that can help in the distinction of anaplastic thyroid carcinomas." (PMID 32632840, 2020). "Therefore, performing PAX8 immunohistochemistry in all samples of thyroid undifferentiated tumors suspicious for ATC, and in particular in squamous subtypes, allows for support of a differential diagnosis with squamous cell carcinoma of the head and neck which is always negative for PAX8." (PMID 35205809, 2022).
thyroid dysgenesis (17 papers, 2010 to 2025). "In cohorts from different geographic regions, PAX8 mutations have been reported in 0.5–3.3% of patients with thyroid dysgenesis." (PMID 41303336, 2025). "Although it represents one of the leading recognized genetic causes of thyroid dysgenesis, the overall reported prevalence of PAX8 gene mutations in cohorts consisting of patients with thyroid dysgenesis is low." (PMID 41303336, 2025). "PAX8 mutations have been chiefly described in patients with CH and thyroid dysgenesis, some of whom also have renal and urinary malformations." (PMID 33692749, 2020). "In conclusion, we have investigated PAX8 mutations in a large cohort of unrelated Chinese CH patients with thyroid dysgenesis and identified several novel PAX8 mutations." (PMID 28060725, 2017). "This is consistent with the reported low prevalence of PAX8 mutations in thyroid dysgenesis in other ethnic populations and another Chinese population." (PMID 28060725, 2017). "Homozygous Pax8 knockout resulted in thyroid aplasia in mice and heterozygous loss-of-function PAX8 mutations were associated with various forms of thyroid dysgenesis in humans, genetically implicating the role of PAX8 defect in thyroid dysgenesis." (PMID 28060725, 2017). "The aim of the present study was thus to screen for PAX8 mutations in a large cohort of Chinese children with thyroid dysgenesis-caused CH and selectively functionally characterize the novel mutations identified here and in a previous study of ours." (PMID 28060725, 2017). "This is the first report on the prevalence documentation and functional characterization of PAX8 mutations in a large cohort of patients with CH from thyroid dysgenesis in Chinese population; it is also the largest study on PAX8 mutations in CH in general." (PMID 28060725, 2017). "Most of the inactivating PAX8 mutations in thyroid dysgenesis have been located in the mutational hotspots of exons 3 and 4 of PAX8—corresponding to the DNA-binding paired domain." (PMID 28060725, 2017). "We screened 453 unrelated Chinese patients with CH from thyroid dysgenesis for PAX8 mutations by sequencing the whole coding regions of PAX8 on genomic DNA isolated from blood." (PMID 28060725, 2017). "In this large cohort of 453 Chinese thyroid dysgenesis patients, we identified three novel PAX8 mutations, including D94N, PAX8 c.1064C>T/p.A355V (rs145036350), and PAX8 c.-26G>A in CH." (PMID 28060725, 2017). "For example, in 17 different ethnic cohorts of thyroid dysgenesis patients, the prevalence of PAX8 mutations was found to be, on average, 1.0%, ranging from 0 to 3.4%." (PMID 28060725, 2017). "Based on mutations in PAX8 is associated with thyroid dysgenesis." (PMID 28060725, 2017). "Consistent with the present study on Chinese patients, a number of mutations have been reported in the coding regions of PAX8, particularly in the paired box domain, which cause loss of function of PAX8 and result in CH with various degree of thyroid dysgenesis in other ethnic populations." (PMID 28060725, 2017). "Mutations in TTF-1, NKX2.1, or PAX-8 genes are found in only 2% of cases of thyroid dysgenesis." (PMID 20537182, 2010). "Patients with these PAX8 mutations either had thyroid agenesis or eutopic normal-sized thyroid gland with weak fixation, suggesting that these mutations were the cause of the thyroid dysgenesis in the patients, which were confirmed by our demonstration of the functional defects of the mutants." (PMID 28060725, 2017). "These cases of patients also show that different PAX8 mutations may cause different thyroid phenotypes of thyroid dysgenesis, which is well explained by the different effects of D94N and G41V on the transcribing activity and binding ability of PAX8 at the promoters of the target genes TPO and TG." (PMID 28060725, 2017). "Pax-8, Ttf-1, and Ttf-2 are transcription factors crucial to thyroid organogenesis and their absence results in varying degrees of thyroid dysgenesis." (PMID 33806425, 2021).
thyroid dysgenesis (continued). "The possible causes of thyroid dysgenesis include the impact of maternal antithyroid immunoglobulins, genetic mutations, and genes of transcription factors, such as TITF1/NKX2–1, PAX8, FOXE1, and HHEX." (PMID 34713843, 2021). "The results also provide new evidence for a dominant negative role of PAX8 mutants as a disease mechanism in the development of CH from thyroid dysgenesis." (PMID 28060725, 2017). "Mutations in the genes for TSH receptor, NKX2-1 (thyroid transcription factor 1), thyroid transcription factor 2, and paired box transcription factor 8 (PAX8) have been identified in some patients with various forms of thyroid dysgenesis." (PMID 28060725, 2017). "Notably, eight mutations in four genes (FOXE1, NKX2-1, PAX8 and HHEX) that lead to thyroid dysgenesis were identified in eight probands." (PMID 29650690, 2018). "Additionally, 21.21% (28/132) of mutations were related to thyroid dysgenesis [TSHR (n = 19), TTF1 (n = 5), TTF2 (n = 1), PAX8 (n = 2), and NKX2-5 (n = 1)]." (PMID 30420871, 2018). "“PAX8 gene” mutation has been found to be associated with various forms of thyroid dysgenesis, whereas TTF-1 gene mutation has been found to be associated with thyroid agenesis or dysgenesis." (PMID 26634164, 2015). "In the absence of transcription factor TTF1, the thyroid gland, including the C-cells that produce calcitonin, will not form, while the absence of transcription factor PAX8 will result in thyroid agenesis, resulting in athyreotic Pax8−/− pups dying within a few weeks of birth." (PMID 35456949, 2022).
clear cell carcinoma (16 papers, 2010 to 2026). "The component of clear cell carcinoma showed a nuclear positive reaction against PAX8 and napsin A, as well as a loss of ARID1A, suggesting typical endometriosis-derived clear cell carcinoma." (PMID 35327349, 2022). "Histologically, the tumor displayed the classic features of clear cell carcinoma, which were supported by positive PAX8 and napsin A immunostaining." (PMID 41983808, 2026). "Morphologically, CDX2- and PAX8-expressing subtypes resembled intestinal-type adenocarcinoma and clear cell carcinoma (occurring in gynecological organs), respectively." (PMID 37510152, 2023). "PAX-8 staining is much less frequent (40%) despite that it is almost universally positive (95–100%) in ovarian serous, endometrioid, and clear cell carcinomas." (PMID 27231561, 2015). "In the series of these authors, PAX8 staining was positive for all the clear-cell carcinoma (10/10), so they concluded that PAX8 was particularly useful for the diagnosis of this histotype." (PMID 20492709, 2010). "Generally, clear cell carcinomas display a CK7(+)/CK20(-) phenotype; express PAX-8; and lack expression of ER and WT-1." (PMID 27231561, 2015). "Renal-derived clear-cell carcinoma was commonly positive for CD10, PAX8, and Vimentin." (PMID 36727056, 2022). "PAX8 is positive in most ovarian nonmucinous surface epithelial tumors: serous, clear cell, and endometrioid cell types, especially for endometrioid and clear cell carcinoma, in which WT1 is generally negative or only focally positive." (PMID 27047697, 2016). "PAX8 is usually highly, but not always, expressed in serous-papillary (96,4%), endometrioid (88,9%) or clear-cell carcinoma (100%)." (PMID 20492709, 2010). "Interestingly, endometrioid and clear cell carcinomas also express PAX8 in the majority of tumors, although these subtypes do not originate from PAX8-positive FTSEC." (PMID 35806410, 2022). "Clear cell carcinoma of the biliary tract should be positive for CK7 and negative for RCC and PAX8, whereas metastatic clear cell renal cell carcinoma would show the reverse pattern." (PMID 24804133, 2014). "However, the tumor was negative for PAX8, WT-1, ER, and PR and showed only focal positivity for EMA, which is inconsistent with the typical immunophenotype of clear cell carcinoma." (PMID 41149460, 2025).
lung adenocarcinoma (16 papers, 2015 to 2025). A carcinoma that arises from the lung and is characterized by the presence of malignant glandular epithelial cells. "Immunohistochemical staining demonstrated positivity for thyroid transcription factor-1 (TTF-1) and negativity for paired box gene 8 (PAX8) and thyroglobulin, consistent with a diagnosis of a primary lung adenocarcinoma (T1bN0M0 stage IA2)." (PMID 41281732, 2025). "The immunostains show positivity to TTF1, napsin A, and CK7 and negativity to PAX8 and CD10 of the neoplastic cells, sustaining a pulmonary phenotype; therefore, we signed the report as primary lung adenocarcinoma with clear cell features." (PMID 38256374, 2024). "In this case, the immunohistochemical results of CK7, Napsin A and TTF-1 supporting the diagnosis of lung adenocarcinoma were all positive, and the immunohistochemical results of Vimentin, CD10 and PAX-8 supporting the diagnosis of RCCC were all positive." (PMID 35979370, 2022). "The immunostains TTF-1, thyroglobulin, PAX8, and Napsin-A are markers that are used in the differential diagnosis of PTC from primary lung adenocarcinoma." (PMID 27774331, 2016). "IHC was positive for TTF and CK-7 and negative for PAX-8 and P40, guiding to a diagnosis of lung adenocarcinoma and, at the same time, ruling out cervical SCC metastasis." (PMID 41220471, 2025). "In particular, histochemistry showed positive for NapsinA and TTF-1, and negative for renal origin marker PAX-8 which proved it was lung adenocarcinoma metastases to the kidney." (PMID 37161448, 2023). "In these instances, PAX-8 can sometimes help in the differential diagnosis of thyroid malignancy versus lung malignancy in that lung adenocarcinomas are typically negative for PAX-8." (PMID 27774331, 2016). "Lung adenocarcinoma cells were in general strongly positive for NKX2-1 but negative for the thyroid-specific transcription factor PAX8, which is consistent with histopathological features of NSCLC." (PMID 37534159, 2023). "TTF-1 and Napsin A were expressed in all 7 cases, and metastatic lung adenocarcinoma was further supported with the negative results for PAX8, HNF-1β, ER and PR, and history of lung adenocarcinoma." (PMID 31455365, 2019).
clear cell renal cell carcinoma (14 papers, 2014 to 2025). "The lineage transcription factor PAX8 is shown to play a pivotal part in determining cancer risk in clear cell renal cell carcinoma, providing insights into how genetic mutations lead to specific types of cancer." (PMID 35676472, 2022). "Pax8 is a crucial transcription factor for organogenesis of the thyroid gland, kidney, and müllerian system and is highly found in highly ovarian and renal clear cell carcinomas." (PMID 30117003, 2018). "Here, we have used CRISPR-Cas9-based genetic screening to demonstrate that loss of SMARCB1, a member of the SWI/SNF chromatin remodeling complex, can confer an advantage to clear cell renal cell carcinoma (ccRCC) cells upon inhibition of the renal lineage factor PAX8." (PMID 37554444, 2023). "Diagnosis of renal hemangioblastoma is challenging because of its rarity and overlapping microscopic and immunophenotypical features with renal cell tumors (PAX8+ and CD10+), especially clear cell renal cell carcinoma." (PMID 35220972, 2022). "Metastatic clear cell renal cell carcinomas show nests of tumor cells surrounded by prominent delicate sinusoidal vessels and are positive for cytokeratin, EMA, PAX-8, and CA9." (PMID 32316685, 2020). "Metastatic clear cell renal cell carcinomas show nests of tumor cells surrounded by prominent delicate vessels and are positive for cytokeratin, EMA, PAX-8, and CA9." (PMID 32316685, 2020). "As the execution of immunohistochemical analyses is often mandatory, the expression of PAX8 has been traditionally considered a reliable marker of metastatic clear cell renal cell carcinoma, being consistently negative in intracranial HB." (PMID 39807616, 2025). "Although clear cell morphology was present, immunostaining was negative for CA-IX and PAX-8, confirming the negative results for metastatic clear cell renal cell carcinoma." (PMID 38836164, 2024). "One case showed clear cells resembling clear cell renal cell carcinoma, and the differential diagnosis was resolved by immunohistochemistry for PAX8: neoplastic cells were positive for β-catenin and negative for PAX-8." (PMID 35204541, 2022). "Clear cell renal cell carcinomas are positive for paired box 8 (PAX8) and negative for Hep Par-1." (PMID 37761023, 2023).